EIF3E (eukaryotic translation initiation factor 3 subunit E)
Description:
Component of the eukaryotic translation initiation factor 3 (eIF-3) complex, which is required for several steps in the initiation of protein synthesis. The eIF-3 complex associates with the 40S ribosome and facilitates the recruitment of eIF-1, eIF-1A, eIF-2:GTP:methionyl-tRNAi and eIF-5 to form the 43S pre-initiation complex (43S PIC). The eIF-3 complex stimulates mRNA recruitment to the 43S PIC and scanning of the mRNA for AUG recognition. The eIF-3 complex is also required for disassembly and recycling of post-termination ribosomal complexes and subsequently prevents premature joining of the 40S and 60S ribosomal subunits prior to initiation. The eIF-3 complex specifically targets and initiates translation of a subset of mRNAs involved in cell proliferation, including cell cycling, differentiation and apoptosis, and uses different modes of RNA stem-loop binding to exert either translational activation or repression. Required for nonsense-mediated mRNA decay (NMD); may act in conjunction with UPF2 to divert mRNAs from translation to the NMD pathway. May interact with MCM7 and EPAS1 and regulate the proteasome-mediated degradation of these proteins.
Synonyms: EIF3S6; INT6; eIF3-p48; eIF3-p46
Tractability: Small molecule: a structure with a bound ligand is known. PROTAC: ubiquitination databases record sites on it; its protein half-life has been measured.
Gene: Protein-coding gene on chromosome 8 (108,162,787 to 108,443,496, reverse strand). Ensembl gene ENSG00000104408.
Subcellular location: Cytoplasm; Nucleus, PML body
Subcellular location (Human Protein Atlas): Cytosol
Pathways (Reactome):
Metabolism of proteins: Formation of a pool of free 40S subunits; Formation of the ternary complex, and subsequently, the 43S complex; GTP hydrolysis and joining of the 60S ribosomal subunit; L13a-mediated translational silencing of Ceruloplasmin expression; Ribosomal scanning and start codon recognition; Translation initiation complex formation
Gene Ontology:
Molecular function: cadherin binding; protein binding; RNA binding; translation initiation factor activity
Biological process: nuclear-transcribed mRNA catabolic process, nonsense-mediated decay; positive regulation of translation; translational initiation; formation of cytoplasmic translation initiation complex; negative regulation of translational initiation; regulation of translational initiation; cytoplasmic translational initiation
Cellular component: cytoplasm; cytosol; eukaryotic translation initiation factor 3 complex; extracellular exosome; membrane; nucleus; PML body; chromatin; eukaryotic translation initiation factor 3 complex, eIF3e; nucleoplasm; eukaryotic 43S preinitiation complex; eukaryotic 48S preinitiation complex; postsynaptic density; protein-containing complex
Genetic constraint (gnomAD): Loss-of-function variants: 21 observed, 36.67 expected, observed/expected ratio (o/e) 0.57, 90% interval 0.41 to 0.82. The upper end of that interval is the gene's LOEUF score, 0.82, which puts it in group 3 of 6, group 1 being the genes least tolerant of losing a copy. Missense variants: 258 observed, 435.26 expected, observed/expected ratio (o/e) 0.59, 90% interval 0.54 to 0.66. Synonymous variants: 149 observed, 137.91 expected, observed/expected ratio (o/e) 1.08, 90% interval 0.94 to 1.24.
Cancer hallmarks: angiogenesis (suppresses); escaping programmed cell death (promotes); invasion and metastasis (suppresses); proliferative signalling (promotes)
Homologues: Orthologues: chimpanzee EIF3E (100% identical), guinea pig EIF3E (100% identical), macaque EIF3E (100% identical), mouse Eif3e (100% identical), rabbit EIF3E (100% identical), pig EIF3E (98% identical), rat Eif3el1 (97% identical), rat Eif3el1 (95% identical), dog EIF3E (94% identical), zebrafish eif3ea (93% identical), tropical clawed frog eif3e (92% identical), zebrafish eif3eb (82% identical), and 3 more.